MYH3 (myosin heavy chain 3)
Description:
Muscle contraction.
Synonyms: MYHC-EMB; MYHSE1; HEMHC; SMHCE; CPSFS1A; CPSFS1B; CPSKF1A; CPSKF1B; DA2A; DA2B; DA2B3; DA8
Tractability: PROTAC: ubiquitination databases record sites on it.
Gene: Protein-coding gene on chromosome 17 (10,628,526 to 10,657,309, reverse strand). Ensembl gene ENSG00000109063.
Subcellular location: Cytoplasm, myofibril
Pathways (Reactome):
Muscle contraction: Striated Muscle Contraction
Gene Ontology:
Molecular function: actin filament binding; ATP hydrolysis activity; microfilament motor activity; calmodulin binding; myosin phosphatase activity; ATP binding; cytoskeletal motor activity
Biological process: ATP metabolic process; skeletal muscle contraction; actin filament-based movement; embryonic limb morphogenesis; face morphogenesis; muscle contraction; muscle filament sliding; muscle organ development; sarcomere organization
Cellular component: extracellular exosome; cytoplasm; cytosol; muscle myosin complex; myosin filament; myosin II complex; sarcomere; contractile muscle fiber; myofibril; myosin complex
Genetic constraint (gnomAD): Loss-of-function variants: 126 observed, 241.78 expected, observed/expected ratio (o/e) 0.52, 90% interval 0.45 to 0.6. The upper end of that interval is the gene's LOEUF score, 0.6, which puts it in group 2 of 6, group 1 being the genes least tolerant of losing a copy. Missense variants: 1,841 observed, 2,476.8 expected, observed/expected ratio (o/e) 0.74, 90% interval 0.71 to 0.77. Synonymous variants: 878 observed, 969.4 expected, observed/expected ratio (o/e) 0.91, 90% interval 0.86 to 0.96.
Homologues: Orthologues: chimpanzee MYH3 (99% identical), macaque MYH1 (99% identical), rat Myh3 (98% identical), guinea pig MYH3 (98% identical), mouse Myh3 (98% identical), dog MYH3 (98% identical), pig MYH3 (96% identical). Paralogues in human: MYH2 (85% identical), MYH8 (85% identical), MYH1 (84% identical), MYH4 (83% identical), MYH13 (79% identical), MYH6 (79% identical), MYH7 (79% identical), MYH7B (67% identical), MYH15 (60% identical), MYH11 (42% identical), MYH10 (41% identical), MYH9 (41% identical), and 32 more.
Diseases named in the same sentence as MYH3 in open-access papers:
MYH3 is named in the same sentence as 57 diseases in open-access papers, as found by Europe PMC text mining. Sharing a sentence is not in itself a finding about the gene and the disease. The quoted sentences say what the papers report.
Freeman-Sheldon syndrome (22 papers, 2007 to 2025). A very rare, multiple congenital contractures syndrome characterized by a microstomia with a whistling appearance of the mouth, distinctive facies, club foot and joint contractures. "Pathogenic variants in MYH3 cause distal arthrogryposis type 2A and type 2B3 as well as contractures, pterygia and spondylocarpotarsal fusion syndromes types 1A and 1B." (PMID 35169139, 2022). "Mutations in MYH3 are associated with Freeman-Sheldon syndrome (FSS), a form of DA characterized by a small mouth and joint contractures." (PMID 34356068, 2021). "Mutations at this site (MYH3 residue 375) in the embryonic skeletal muscle isoform, MYH3, cause Freeman-Sheldon syndrome." (PMID 34943138, 2021). "For instance, MYH3 is the only gene associated with Freeman-Sheldon syndrome (and the only gene associated with DA8–autosomal dominant MPS)." (PMID 34356068, 2021). "Different mutations spanning the MYH3 coding region have been associated with Freeman-Sheldon syndrome (FSS), the most severe form of DA, and Sheldon-Hall syndrome (SHS), the milder and most common form of DA." (PMID 26544689, 2015). "At least 18 mutations in the globular head and rod domains of MYH3 have been associated with DA1, DA2A (Freeman–Sheldon syndrome) and DA2B (Sheldon–Hall syndrome)." (PMID 22918376, 2013). "MYH3 had previously been identified as the gene underlying Freeman Sheldon syndrome via careful selection of candidate causal genes for sequencing based on similarity to other Mendelian disorders with known genetic causes." (PMID 23819870, 2013). "Germline variants in MYH3 are associated with distal arthrogryposis syndromes [distal arthrogryposis type 1, Freeman-Sheldon syndrome (DA2A), and Sheldon-Hall syndrome (DA2B)], multiple pterygium syndrome (MPS), and spondylocarpotarsal synostosis syndrome (SCT)." (PMID 30967136, 2019). "The distal arthrogryposis type 2A can be caused by mutation in the MYH3 gene." (PMID 20090872, 2009). "Secondly, in a separate study, various mutations in MYH3 [MIM 160720] encoding embryonic myosin heavy chain have been causally linked to the occurence of the Freeman-Sheldon syndrome [MIM 193700] and the Sheldon-Hall syndrome (alternatively designated type 2B distal arthrogryposis [MIM 601680])." (PMID 18159245, 2007). "Freeman-Sheldon syndrome (FSS) is a rare congenital disorder characterized by arthrogryposis, also known as distal arthrogryposis (DA) type 2A, due to mutations in the MYH3 gene." (PMID 39835054, 2024). "Studies have reported the contributing factors of MYH3 towards distal arthrogryposis type I, 2A (Freeman-Sheldon syndrome) and 2B (Sheldon-Hall syndrome), contractures, pterygia, and variable skeletal fusions syndrome 1A (OMIM 178110) and 1B (OMIM 618469)." (PMID 32315303, 2020). "DA2A, Freeman–Sheldon syndrome, and DA2B, Sheldon–Hall syndrome, have been reported as the first disorders associated with mutations in embryonic MyHC (MYH3)." (PMID 26537820, 2015). "Considering only genes that contained variants in all cases, the VEST gene score ranked dihydroorotate dehydrogenase (DHODH) number 2 of 2253 genes in four cases of Miller syndrome, and myosin-3 (MYH3) number 2 of 2313 genes in three cases of Freeman Sheldon syndrome." (PMID 23819870, 2013). "Although studies have reported the contributing factors of MYH3 towards various syndromes including distal arthrogryposis type I, 2A (Freeman-Sheldon syndrome) and 2B (Sheldon-Hall syndrome), the association of MYH3 towards heart abnormalities in humans has not been reported." (PMID 32315303, 2020).
scoliosis (11 papers, 2018 to 2025). A congenital or acquired spinal deformity characterized by lateral curvature of the spine. "A disease associated with malfunction of the MYH3 gene is characterised by scoliosis, contractures of the V fingers, knees and elbows, dysplasia of the calf muscles, foot deformity and limb length asymmetry." (PMID 38275606, 2024). "We would suggest further investigation into the specific gene mutations of MYH3 that leads to the occurrence of scoliosis." (PMID 34356068, 2021). "Germline loss of Myh3 in mice results in altered muscle fiber size, fiber number, fiber type, and misregulation of genes, and adult Myh3 null mice develop scoliosis." (PMID 34203046, 2021). "It is possible that abnormal mechanical forces imposed upon the intervertebral disk by pathogenic MYH3 mutations functioning postnatally in these small muscle increase the vulnerability of the spine to scoliosis and spinal fusions over time." (PMID 33016623, 2020). "Understanding the differences in the specific mutations of MYH3 between these three conditions may shed light on the origins of scoliosis." (PMID 34356068, 2021). "We find that Myh3 germline knockout adult mice display SCTS phenotypes such as scoliosis and vertebral fusion, in addition to reduced body weight, muscle weight, myofiber size, and grip strength." (PMID 37492882, 2023). "This led to increased muscle fiber size, rescue of most muscle fiber type alterations, normalization of the satellite cell marker Pax7 levels, increased grip strength, reduced fibrosis, and decline in scoliosis in Myh3 knockout mice." (PMID 37492882, 2023). "Myh3 germline knockout adult mice also exhibit scoliosis and vertebral fusion, increase in MyHC‐IIb and ‐IIa fiber types and decrease in MyHC‐slow fiber type, muscle‐type, and age‐dependent alterations in satellite cell numbers and increased muscle fibrosis." (PMID 37492882, 2023). "Some of the most severe abnormalities seen in SCTS are vertebral fusion and scoliosis, which are also seen in Myh3 knockout mice." (PMID 37492882, 2023). "Among these, recessive loss‐of‐function MYH3 mutations lead to spondylocarpotarsal synostosis (SCTS), characterized by vertebral fusions and scoliosis." (PMID 37492882, 2023). "Interestingly the MYH3 c.-9+1G > A variant was initially described in individuals with spondylocarpotarsal synostosis syndrome, but the reported phenotype also included webbing, contractures and scoliosis and thus had considerable overlap with the clinical characteristics of our patients." (PMID 34440395, 2021). "Moreover, scoliosis and short stature, presented by our patients, appear to be overlapping features in all MYH3 patients previously reported." (PMID 41180161, 2025). "MYH3 encodes embryonic myosin and its mutations contribute to spondylocarpotarsal synostosis (SCT), which is a skeletal disorder characterized by fused vertebrae (including scoliosis and lordosis) and fused carpal and tarsal joints." (PMID 30241458, 2018).
arthrogryposis (7 papers, 2018 to 2025). A rare, non-progressive congenital disorder characterized by multiple joint contractures which are present at birth. "This article extends the phenotype of MYH3-associated arthrogryposis to include movement disorders, illustrating a family of four children presenting MYH3 skeletal disorders and lingual dystonia." (PMID 41180161, 2025). "In this study we extend the phenotypic spectrum of MYH3-associated disorders reporting additional 17 affected individuals from 10 unrelated families with vertebral fusions, arthrogryposis and multiple pterygia." (PMID 35169139, 2022). "In humans, dominant non-synonymous MYH3 mutations cause distal arthrogryposis such as in the Freeman-Sheldon (FSS) and Sheldon-Hall (SHS) syndromes, which are characterized by multiple facial and limb congenital contractures." (PMID 36309651, 2022). "Among them, the MYH3 gene causes several types of arthrogryposis conditions and therefore has a pivotal role in the skeletal and muscle development of the fetus." (PMID 32767732, 2020). "Distal arthrogryposis is a cause of syndromic TEV that is characterized by variations in genes that encode for components of the muscle contractile complex (MYH3, TPM2, TNNT3, TNNI2, and MYH8), resulting in muscle contractures." (PMID 30134936, 2018). "We have extended the phenotype of MYH3-associated arthrogryposis to include movement disorders, which may have been underdiagnosed to date." (PMID 41180161, 2025).
Sheldon-hall syndrome (7 papers, 2007 to 2025). Sheldon-Hall syndrome (SHS) is a rare multiple congenital contracture syndrome characterized by contractures of the distal joints of the limbs, triangular face, downslanting palpebral fissures, small mouth, and high arched palate. "Heterozygous variants in MYH3 cause Sheldon-Hall syndrome (SHS) or FSS, characterized by distinctive facial features, hand and foot contractures, camptodactyly, oropharyngeal defects, and scoliosis." (PMID 41510282, 2025). "MYH3 mutations can also lead to DA1, the “classic” distal arthrogryposis, as well as DA2B, Sheldon-Hall syndrome, both of which rarely have associated scoliosis." (PMID 34356068, 2021).
spondylocarpotarsal synostosis syndrome (6 papers, 2019 to 2023). "The phenotypic spectrum of MYH3‐associated disease was recently broadened to include vertebral fusions, which are a defining clinical feature of spondylocarpotarsal synostosis syndrome." (PMID 33016623, 2020). "Interestingly, MYH3 was also shown to be expressed in bone, which the authors state may explain the effects of MYH3 variants on both skeletal muscle and bone, particularly for patients with spondylocarpotarsal synostosis syndrome and bony fusions." (PMID 34203046, 2021). "Mutations in MYH3, which encodes embryonic heavy chain (MyHC) expressed initially during slow skeletal muscle development are also associated with multiple pterygium syndrome (MPS) and spondylocarpotarsal synostosis syndrome." (PMID 34356068, 2021). "However, the molecular defect may make these mice a better model for recessive MYH3 spondylocarpotarsal synostosis syndromes than for autosomal dominant DA." (PMID 34203046, 2021).
multiple pterygium syndrome (5 papers, 2017 to 2025). "Only two parents with pathogenic variants in the TNNI3 and MYH3 gene, had clinical manifestations consistent with cardiomyopathy and multiple pterygium syndrome, respectively." (PMID 41256177, 2025).
distal arthrogryposis (3 papers, 2023 to 2026). A muscle tissue disease characterized by congenital joint contractures of hand and feet. "We hereby report a nuclear family affected by distal arthrogryposis with biallelic MYH3-related disorder, identifying two novel variants, which in the heterozygous state yield a subclinical phenotype." (PMID 41562327, 2026). "Distal arthrogryposis, a syndromic form of TEV, is characterized by mutations in genes that encode components of the muscle contractile complex, such as myosin heavy chain 3 (MYH3), TPM2, TNNT3, TNNI2, and MYH8, leading to muscle contractures." (PMID 40746736, 2025).
distal arthrogryposis type 1 (3 papers, 2019 to 2021). "MYH3 mutations have been identified in multiple DA syndromes, including distal arthrogryposis, type 1, DA2A, and distal arthrogryposis type 2B (DA2B) (also called Sheldon‐Hall syndrome)." (PMID 33016623, 2020).
Duchenne muscular dystrophy (3 papers, 2024 to 2025). Duchenne muscular dystrophy (DMD) is a neuromuscular disease characterized by rapidly progressive muscle weakness and wasting due to degeneration of skeletal, smooth and cardiac muscle. "Hence, drawing from the observations made in Duchenne muscular dystrophy, we analyzed the expression of MYH3 in our patients and found a pronounced upregulation in sarcopenic muscle from DP, together with a downregulation of the adult myosin isoform MYH2." (PMID 38338718, 2024).
Autosomal dominant multiple pterygium syndrome (2 papers, 2021 to 2023). "Moreover, MYH3 mutations are associated with distal arthrogryposis type 8." (PMID 34440395, 2021). "as possibly having autosomal dominant multiple pterygium syndrome (MIM: 178110), but no likely pathogenic or pathogenic variants in MYH3 were identified." (PMID 37457373, 2023).
Escobar syndrome (2 papers, 2021 to 2022). "This seems to be particularly true for patients with MYH3 mutations underlying their Escobar syndrome." (PMID 34440395, 2021). "While CHRNG mutations caused Escobar syndrome for 75 patients of known cases, a number of patients had a genetic etiology associated with variants in the TPM2, CHRND, CHRNA1, MUSK, MYH3, RAPSN, and DOK7 genes." (PMID 36292632, 2022).
Insulin resistance (2 papers, 2021 to 2025). Increased resistance towards insulin, that is, diminished effectiveness of insulin in reducing blood glucose levels. "Specific slow type myosin heavy chain components were associated with AL (MYH7) and BI (MYH3) pigs, while an overexpression of MAP3K14 in AL may be associated with their lower loin proportion, induced insulin resistance, and increased inflammatory response via NFkB activation." (PMID 34065673, 2021). "GWIS identified ten SNPs in three loci, including rs4713207 (OR14J1, Pmeta = 3.95 × 10−8) for insulin resistance, rs17708475 (NKAIN2, Pmeta = 4.83 × 10−8) for insulin sensitivity, and rs201613 (MYH3, Pmeta = 1.05 × 10−8) for disposition index." (PMID 40719081, 2025).
sarcopenia (2 papers, 2023 to 2024). Progressive decline in muscle mass due to aging which results in decreased functional capacity of muscles. "Among older dependent individuals with sarcopenia, there was a significant increase in the MYH3/MYH2 ratio, indicating a transcriptional shift in expression from mature to developmental myosin isoforms." (PMID 38338718, 2024). "Consistently with the findings in dystrophic muscle of mdx mice, we found a sharp upregulation of the MYH3/MYH2 ratio in dependent elderly with sarcopenia indicating a shift in myosin isoform expression from the mature to the embryonic form, which recapitulates a feature of DMD." (PMID 38338718, 2024). "Finally, we identified the gene expression of MYH3 and the MYH3/MYH2 ratio as potential biomarkers of sarcopenia worsening." (PMID 38338718, 2024). "The higher expression of MYH3, in conjunction with the absence of activation of myogenic precursors typically found in healthy regenerating muscle in individuals with sarcopenia, signifies a pathological process of incomplete regeneration that may result in the atrophy of aging muscles." (PMID 38338718, 2024).
breast carcinoma (1 paper, 2024). "A number of studies have shown a significant correlation between MYH3 expression and PTEN mutation in prostate cancer, tongue cancer metastasis, and breast cancer prognosis." (PMID 39684472, 2024).
cleft lip (1 paper, 2025). Congenital defect in the upper lip where the maxillary prominence fails to merge with the merged medial nasal prominences. "This has recently occurred with recessive cleft lip in Limousin cattle due to a frameshift mutation in MYH3, which was initially described by our team as causing juvenile mortality due to feeding difficulties." (PMID 40394457, 2025).
colon adenocarcinoma (1 paper, 2024). "MYH3 has been identified as a gene associated with disulfideptosis in colon adenocarcinoma." (PMID 39684472, 2024).
dwarfism (1 paper, 2009). "DA2A which includes in its phenotype ptosis, dwarfism, small contracted mouth, and proximal and distal joint contractures was found to have MYH3 gene mutations." (PMID 20090872, 2009).
Dystonia (1 paper, 2025). An abnormally increased muscular tone that causes fixed abnormal postures. "Besides muscles and bones, MYH3 is also expressed postnatally in the brain, including the basal ganglia, a region frequently implicated in dystonia pathophysiology." (PMID 41180161, 2025). "Therefore, we postulate that our MYH3 missense variants could inhibit the TGF-beta pathway and may lead to dystonia through the inhibition of this pathway in the basal ganglia." (PMID 41180161, 2025).
glaucoma (1 paper, 2024). Increased pressure in the eyeball due to obstruction of the outflow of aqueous humor. "The underlying pathophysiology connecting FSS with glaucoma remains speculative, as FSS is primarily associated with skeletal and craniofacial abnormalities due to mutations in the MYH3 gene." (PMID 39835054, 2024).
head and neck cancer (1 paper, 2019). A primary or metastatic malignant neoplasm affecting the head and neck. "Slightly elevated mRNA level of MYH3 gene was found in head and neck cancer with average fragments per kilobase million (FPKM) 3.3 in a set of 499 samples." (PMID 30967136, 2019).
joint contractures (1 paper, 2015). "However, the physiological significance of developmental myosins remained completely unclear until 2006, when embryonic (MYH3) mutations were first reported to cause specific syndromes characterized by congenital joint contractures." (PMID 26180627, 2015).
lung carcinoma (1 paper, 2019). "Variants in MYH3 were detected as benzo(a)pyrene exposure-genomic alterations in lung cancer patients." (PMID 30967136, 2019).
non-Hodgkin lymphoma (1 paper, 2024). Distinct from Hodgkin lymphoma both morphologically and biologically, non-Hodgkin lymphoma (NHL) is characterized by the absence of Reed-Sternberg cells, can occur at any age, and usually presents as a localized or generalized lymphadenopathy associated with fever and weight loss. "Our study, supporting the use of five approaches, including TMT, gene ontology (GO), Reactome, KEGG pathway, and molecular docking analyses, suggests that DEPs, Myh3, Eno2, and H4c11 may be three novel biomarkers or therapeutic targets for non-Hodgkin lymphoma." (PMID 39861068, 2024).
Paraparesis (1 paper, 2024). Weakness or partial paralysis in the lower limbs. "Specifically, our case report deals with a unique and rare instance of KFS in a child with a mutated MYH3 gene and neurological manifestations such as paraparesis." (PMID 39590565, 2024).